MPC1 (mitochondrial pyruvate carrier 1)
Diseases named in the same sentence as MPC1 in open-access papers (continued):
Sharing a sentence is not in itself a finding about the gene and the disease.
cancer (continued). "Targeting MPC1 may provide novel insight into the design and assessment of drugs for treating cancers, which may be a promising cancer treatment strategy for patients." (PMID 34059057, 2021). "In addition, MPC1 expression was deeply affected in five cancer types: BRCA, KIRC, LUAD, PAAD, and PRAD." (PMID 34059057, 2021). "Differential expression of MPC1 indicated different prognoses in various cancers." (PMID 34059057, 2021). "MPC1 showed significantly different expression levels across cancers." (PMID 34059057, 2021). "And existing studies have shown that MPC1 could alter the maintenance and fate of stem cells through regulating cancer metabolism in CRC." (PMID 32851100, 2020). "It is well known that CRC is one of the most malignant tumors given its strong metastasis ability, so we tried to figure out whether the MPC1 expression was correlated with metastasis." (PMID 32851100, 2020). "In addition, western blotting revealed that overexpression of MPC1 decreased the level of cancer stem cell (CSC) markers, including NANOG, OCT4, and SOX2 in LAC cells, while knockdown of MPC1 increased the level of these markers." (PMID 30770798, 2019). "In summary, it was shown that decreased MPC1 expression in cancer cells contributed not only to the metastatic potential of the cells but also to the acquisition of resistance to radiation therapy and was involved in improving the cancer survival rate." (PMID 30801869, 2019). "Since MPC1 binds to mito-STAT3 and inhibits the phosphorylation of STAT3, we explored whether MPC1-mediated cancer cell progression depends on the downstream of the STAT3 pathway." (PMID 30770798, 2019). "A significant radiosensitizing effect was also observed in tumors derived from cancer cells expressing two distinct MPC1-targeted shRNA as well as upon administration of UK-5099 compound together with the demonstration of a reduction in hypoxia as revealed by pimonidazole staining." (PMID 29572438, 2018). "Low MPC1 expression is correlated with poor survival in almost all cancers." (PMID 30397542, 2018). "To determine whether MPC1 knockout has a suppression effect on cancer cell proliferation, we firstly explored its influence on cell growth." (PMID 28624784, 2017). "Here, we show that COUP-TFII suppresses MPC1 expression to regulate cancer cell metabolism." (PMID 26895100, 2016). "MPC1 down-regulation mimics a glucose-starved circumstance, which mobilizes or activates usage of different fuel sources to maintain the high levels of precursor pools for cell proliferation, thus promoting cancer progression." (PMID 26895100, 2016). "However, whether and how MPC1 controls mitochondrial oxidative capacity in cancer are still relatively unknown." (PMID 34059057, 2021). "Specifically, propofol was found to downregulate glucose transporter 1 (GLUT1) and mitochondrial pyruvate carrier 1 (MPC1), two key regulators of cancer cell metabolism and energy production." (PMID 40765592, 2025). "It has been reported that the expression of MPC1 and MPC2 is frequently decreased in several types of cancer." (PMID 38615083, 2024). "Our data demonstrated that after sevoflurane administration, the MPC1 and GLUD1 expressions were upregulated, enhancing the activity of the TCA cycle to meet the demands of cancer survival and progression." (PMID 36207479, 2023). "A study showed that the suppression of MPC1 expression changed metabolic and EMT traits and increased mitochondrial ROS and lipid peroxidation, inducing ferroptosis in cancer cells." (PMID 36009223, 2022). "Lysine demethylase 5A (KDM5A) regulates MPC1 expression, and the KDM5A–MPC1 axis is involved in regulating the mesenchymal characteristics of cancer cells during EMT." (PMID 35968507, 2022). "MPC1 expression is regulated by histone lysine demethylase 5A (KDM5A), and the KDM5A-MPC1 axis promotes cancer cell progression." (PMID 34759927, 2021).
cancer (continued). "To understand the potential importance of MPC function in human HCC, we analyzed MPC1 and MPC2 expression in The Cancer Genome Database (TCGA), a comprehensive multidimensional map of key genomic changes in 33 types of cancer." (PMID 31484072, 2019). "Then, we evaluated the protein level of MPC1 used a tissue microarray containing 392 matching cancer and corresponding adjacent nontumor tissues which subjected IHC staining." (PMID 32851100, 2020). "Moreover, in low MPC1 expression, radioresistance is induced, which suggests that it is important to understand MPC and cancer metabolism as novel targets for cancer therapy." (PMID 30801869, 2019). "Decreased MPC1 expression favorably affects EMT and radioresistance of cancer." (PMID 30801869, 2019). "Recent identification of MPC1 and MPC2, genes responsible for pyruvate uptake into the mitochondrial matrix, has added a new complexity to targeting pyruvate metabolism in human disorders, including cancer." (PMID 28397687, 2017). "Much like the ADH genes, MPC1 is downregulated in a proliferation-independent manner, and has recently been shown to affect cancer cell line growth in nonadherent, 3D culture conditions but not in proliferation or cell-cycle progression assays." (PMID 26555223, 2015). "In addition to MPC1, the “intersection point” between glycolysis and OXPHOS, we also found the increased expression of lactate dehydrogenase A (LDHA), an enzyme catalyzing the conversion of pyruvate and lactate thus promoting glycolysis and suppressing OXPHOS, in HGLO subgroup across cancer types." (PMID 34030708, 2021). "Glucose is taken up by cancer cells through GLUT1 and transformed to pyruvate, which is converted to lactate rather than enters mitochondria via MPC1 to be utilized by the TCA cycle." (PMID 36207479, 2023).
infection (3 papers, 2022 to 2024). The state of being infected such as from the introduction of a foreign agent such as serum, vaccine, antigenic substance or organism. "Ten weeks post-infection, MPC1 KO T cells were more abundant in the spleen and formed more TCM cells." (PMID 35452600, 2022). "Naive CD45.2+ CD8+ T cells from OT1 Mpc1fl/fl (referred to as WT) and Mpc1fl/flCd4-Cre (referred to MPC1 KO) mice were transferred into CD45.1.2+ mice, followed by infection with Listeria monocytogenes overexpressing SIINFEKL." (PMID 35452600, 2022). "However, at day 7 post-infection, MPC1 KO T cells formed fewer SLECs and more MPECs as well as more central memory T (TCM) cells 4 weeks after infection." (PMID 35452600, 2022).
brain diseases (1 paper, 2024). "The function of MPC1 in brain diseases is still controversial." (PMID 39247825, 2024).
cardiovascular diseases (1 paper, 2020). "In cardiovascular diseases, it has been demonstrated that MPC-1 deficiency results in a substantial reduction in arterial lipid deposition." (PMID 33171640, 2020).
inflammation (1 paper, 2020). Aberrant reaction of the microcirculation characterized by movement of fluid and leukocytes from the blood into extravascular tissues. "Hence, we suspect that MPC1 is involved in bowel inflammation to tumorigenesis." (PMID 32851100, 2020).
kidney disease (1 paper, 2020). "Moreover, both MPC1 and MPC2 levels were significantly correlated with serum creatinine, BUN and eGFR in patients with DN, whereas no analogous trend was observed in the non-diabetic kidney disease group." (PMID 32664896, 2020). "Moreover, both MPC1 and MPC2 levels were significantly correlated with serum creatinine, BUN and eGFR in patients with DN, whereas no analogous trend was observed in nondiabetic kidney disease." (PMID 32664896, 2020).
MPC1 also shares sentences with these, for which no sentence is quoted: Insulin resistance (2 papers); kidney cancer (2); metabolic disorders (2); abortion (1); adenocarcinoma (1); Anxiety (1); Batten disease (1); cervical cancer (1); colon (1); colorectal tumor (1); COVID-19 (1); depression (1); dermatomyositis (1); Failure to thrive (1); Glucose intolerance (1); hepatopathy (1); immune diseases (1); interstitial lung disease (1); intrahepatic cholangiocarcinoma (1); Listeria infection (1); melanoma (1); MELAS (1); metastasis (1); microcephaly (1); mucinous adenocarcinoma (1); Myocardial fibrosis (1); myocardial infarction (1); nonalcoholic fatty liver (1); polymyositis (1); preeclampsia (1).
A further 8 diseases each share a sentence with MPC1 in 1 paper.